ERLEC1 (endoplasmic reticulum lectin 1)
Description:
Probable lectin that binds selectively to improperly folded lumenal proteins. May function in endoplasmic reticulum quality control and endoplasmic reticulum-associated degradation (ERAD) of both non-glycosylated proteins and glycoproteins.
Synonyms: Erlectin; C2orf30; XTP3TPB; CL25084; XTP3-B; CIM; CL24936; HEL117
Tractability: Antibody: UniProt predicts a signal peptide or a membrane-spanning region. PROTAC: ubiquitination databases record sites on it; its protein half-life has been measured.
Gene: Protein-coding gene on chromosome 2 (53,787,009 to 53,833,038, forward strand). Ensembl gene ENSG00000068912.
Subcellular location: Endoplasmic reticulum lumen
Pathways (Reactome):
Disease: Defective CFTR causes cystic fibrosis; Hh mutants are degraded by ERAD
Immune System: AMPK-induced ERAD and lysosome mediated degradation of PD-L1(CD274)
Signal Transduction: Hedgehog ligand biogenesis
Transport of small molecules: ABC-family protein mediated transport
Gene Ontology:
Molecular function: protein binding; protein-macromolecule adaptor activity
Biological process: negative regulation of retrograde protein transport, ER to cytosol; ERAD pathway; retrograde protein transport, ER to cytosol; endoplasmic reticulum unfolded protein response
Cellular component: endoplasmic reticulum lumen; endoplasmic reticulum quality control compartment; Hrd1p ubiquitin ligase complex; luminal surveillance complex; endoplasmic reticulum
Genetic constraint (gnomAD): Loss-of-function variants: 32 observed, 45.44 expected, observed/expected ratio (o/e) 0.7, 90% interval 0.53 to 0.95. The upper end of that interval is the gene's LOEUF score, 0.95, which puts it in group 4 of 6, group 1 being the genes least tolerant of losing a copy. Missense variants: 427 observed, 443.35 expected, observed/expected ratio (o/e) 0.96, 90% interval 0.89 to 1.04. Synonymous variants: 178 observed, 159.81 expected, observed/expected ratio (o/e) 1.11, 90% interval 0.99 to 1.26.
Homologues: Orthologues: chimpanzee ERLEC1 (99% identical), macaque ERLEC1 (99% identical), rabbit ERLEC1 (98% identical), mouse Erlec1 (96% identical), dog ERLEC1 (96% identical), rat Erlec1 (96% identical), pig ERLEC1 (93% identical), guinea pig ERLEC1 (92% identical), tropical clawed frog erlec1 (72% identical), zebrafish erlec1 (62% identical), Drosophila melanogaster CG6766 (33% identical), Caenorhabditis elegans Y105E8A.2 (33% identical). Paralogues in human: OS9 (23% identical).
Diseases named in the same sentence as ERLEC1 in open-access papers:
ERLEC1 is named in the same sentence as 8 diseases in open-access papers, as found by Europe PMC text mining. Sharing a sentence is not in itself a finding about the gene and the disease. The quoted sentences say what the papers report.
interstitial cystitis (1 paper, 2024). A rare chronic debilitating urogenital disease characterized by urinary frequency, urgency, and pelvic pain. "Seven hub genes (SPTBN1, PSME4, CHAC2, ERLEC1, ASB3, STAT5A, and STAT3) were identified as differentially expressed between interstitial cystitis patients and healthy individuals, representing potential therapeutic targets." (PMID 39399486, 2024).
lung carcinoma (1 paper, 2017). "Ectopic expression of ERLEC1 in lung cancer cells increased their tolerance to hypoxia and endoplasmic reticulum stress, protecting the cells from apoptosis, while ERLEC1 knockdown resulted in reduction in metastasis in a mouse xenograft model." (PMID 28698647, 2017).
periodontitis (1 paper, 2022). An acute or chronic inflammatory process that affects the tissues that surround and support the teeth. "Lastly, further studies are required to determine the location of SERPINA1, ERLEC1, and VWF in ERS and investigate the mechanisms by which these three genes are linked to periodontitis." (PMID 36072904, 2022). "SERPINA1, ERLEC1, and VWF showed high diagnostic values (AUC > 0.85), so they were considered as potential biomarkers for periodontitis." (PMID 36072904, 2022). "Three ERS-related genes, SERPINA1, ERLEC1, and VWF, showed valuable biomarker potential for periodontitis, which provide a target base for future studies on early diagnosis and treatment of periodontitis." (PMID 36072904, 2022). "Through machine learning, we identified three potential biomarkers of periodontitis, SERPINA1, ERLEC1, and VWF and found strong correlations between these ERS-related genes and immune cell infiltration." (PMID 36072904, 2022). "After further screening by the validation set, SERPINA1, ERLEC1, and VWF were selected as potential biomarkers of periodontitis." (PMID 36072904, 2022). "In our study, SERPINA1 was the core gene in PPI and correlated with seven ERS-related genes including ERLEC1, VWF, EDEM2, DERL3, APOE, IL6, and CXCL8, suggesting that SERPINA1 may play an essential role in the pathological process of periodontitis." (PMID 36072904, 2022). "However, there are still relatively few studies on ERLEC1, and no studies on the role of ERLEC1 in periodontitis have been reported so far." (PMID 36072904, 2022). "Therefore, SERPINA1, ERLEC1, and VWF were selected as potential biomarkers of periodontitis." (PMID 36072904, 2022).
prostate carcinoma (1 paper, 2017). A carcinoma that arises from epithelial cells of the prostate gland. "Functional analysis of FBXL4 in prostate cancer cell lines suggested its involvement in cell migration and invasion, potentially through regulation of the levels of Endoplasmic Reticulum Lectin 1 (ERLEC1) protein, a regulator of cellular stress-response and promoter of metastatic cell survival." (PMID 28698647, 2017).
cancer (3 papers, 2017 to 2024). A tumor composed of atypical neoplastic, often pleomorphic cells that invade other tissues. "The Erlec1 gene encodes for endoplasmic reticulum lectin 1 and is involved in cell stress response, including endoplasmic reticulum stress, and is frequently overexpressed in human cancers." (PMID 38248237, 2023). "Identification of the proteins which are associated with cell invasion and aggressive disease and whose degradation is controlled by FBXL4, such as ERLEC1, has the potential to develop targeted therapies for a large number of lethal human cancers with loss of FBXL4." (PMID 28698647, 2017). "ERLEC1 is a molecular chaperone that plays a role in the endoplasmic reticulum stress response, and is related to cancer invasion and metastasis." (PMID 37847340, 2024). "One in vitro analysis showed that FBXL4 plays a role in regulating cell migration and invasion, and can prevent cancer metastasis to bones by downregulating ERLEC1." (PMID 37847340, 2024). "FBXL4 potentially controls cancer metastasis through regulation of ERLEC1 levels." (PMID 28698647, 2017). "Thus FBXL4 may prevent cancer metastasis through regulation of ERLEC1 protein levels." (PMID 28698647, 2017).
infection (1 paper, 2012). The state of being infected such as from the introduction of a foreign agent such as serum, vaccine, antigenic substance or organism. "Prior to the infection, B-lymphocytes were the major producers of PRDX4, SEC11C, ERLEC1 and TXNDC5 and all immunoglobulins." (PMID 23094107, 2012). "The expression of PRDX4, SEC11C, ERlEC1 and TXNDC5 decreased in expression in B-lymphocytes after S. Enteritidis infection suggesting a suppression of common B-lymphocyte function and specialization of B-lymphocyte towards immunoglobulin expression after the infection." (PMID 23094107, 2012).
ERLEC1 also shares sentences with these, for which no sentence is quoted: COVID-19 (1 paper); osteosarcoma (1).